ZSWIM5 (zinc finger SWIM-type containing 5)
Synonyms: KIAA1511
Tractability: No criterion of Open Targets' tractability assessment is met for any kind of drug.
Gene: Protein-coding gene on chromosome 1 (45,016,395 to 45,306,209, reverse strand). Ensembl gene ENSG00000162415.
Subcellular location (Human Protein Atlas): Nuclear speckles
Gene Ontology:
Molecular function: zinc ion binding
Cellular component: extracellular region; Cul2-RING ubiquitin ligase complex
Genetic constraint (gnomAD): Loss-of-function variants: 52 observed, 113.59 expected, observed/expected ratio (o/e) 0.46, 90% interval 0.37 to 0.58. The upper end of that interval is the gene's LOEUF score, 0.58, which puts it in group 2 of 6, group 1 being the genes least tolerant of losing a copy. Missense variants: 1,108 observed, 1,444.4 expected, observed/expected ratio (o/e) 0.77, 90% interval 0.73 to 0.81. Synonymous variants: 487 observed, 564 expected, observed/expected ratio (o/e) 0.86, 90% interval 0.8 to 0.93.
Homologues: Orthologues: chimpanzee ZSWIM5 (99% identical), macaque ZSWIM5 (99% identical), dog ZSWIM5 (97% identical), pig ZSWIM5 (97% identical), mouse Zswim5 (96% identical), rat Zswim5 (96% identical), guinea pig ZSWIM5 (90% identical), rabbit ZSWIM5 (88% identical), tropical clawed frog zswim5 (82% identical), zebrafish zswim5 (81% identical). Paralogues in human: ZSWIM6 (72% identical), ZSWIM4 (62% identical), ZSWIM8 (28% identical).
Diseases named in the same sentence as ZSWIM5 in open-access papers:
ZSWIM5 is named in the same sentence as 3 diseases in open-access papers, as found by Europe PMC text mining. Sharing a sentence is not in itself a finding about the gene and the disease. The quoted sentences say what the papers report.
glioma (1 paper, 2019). A benign or malignant brain and spinal cord tumor that arises from glial cells (astrocytes, oligodendrocytes, ependymal cells). "Among these key genes, ZSWIM5 was the most up regulated, which plays a possible role in nerve conduction formation, and was considered as high cytoplasmic expression gene of interest for human glioma." (PMID 31464612, 2019).
cancer (2 papers, 2019 to 2025). A tumor composed of atypical neoplastic, often pleomorphic cells that invade other tissues. "ZSWIM8 is expressed in various cancer cells, including papillary thyroid carcinoma, non-small cell lung cancer, and human glioma, while ZSWIM5 is involved in embryonic and neural development." (PMID 41007757, 2025). "In addition to ZSWIM8, other members of the SWIM-type zinc finger family, including ZSWIM4, ZSWIM5, and ZSWIM6, have been implicated as potential cancer targets and biomarkers." (PMID 41007757, 2025). "Although this analysis was carried out in only the 6 cancer cases, the correlations between deltaβ and time to diagnosis were significant for the CpGs in the promoter region of REC8, and introns of RPTOR and ZSWIM5." (PMID 31149338, 2019).
tumor (1 paper, 2019). "There is also evidence that KCNQ1 (potassium voltage-gated channel member), MTA3, and ZSWIM5 (zinc finger SWIM-type 5) have tumor suppressive roles." (PMID 31149338, 2019).